TPO (thyroid peroxidase)
Diseases named in the same sentence as TPO in open-access papers (continued):
Sharing a sentence is not in itself a finding about the gene and the disease.
thyroid cancer (continued). "The expression of TG, NIS, PDS, and TPO was significantly lower in pediatric thyroid carcinomas compared to the normal thyroid tissue (P < 0.05)." (PMID 27022395, 2016). "Downregulation of TPO has been considered in a number of studies comparing thyroid carcinoma with thyroid carcinomas with benign thyroid tumors or normal thyroid samples." (PMID 25922907, 2015). "Thyroid mRNAs such as Tg, TSHR, TPO mRNA has been widely used to detect recurrence or metastasis of thyroid carcinoma as this mRNA showed good sensitivity and specificity for DTC." (PMID 26244057, 2015). "TPO gene and protein expression in thyroid carcinoma have been analyzed, indicating low enzymatic activity, impaired solubility and suppressed TPO mRNA expression." (PMID 26300979, 2015). "To study the function of Snail in thyroid cancer cells, we developed a thyroid cancer cell line (the Marca cell line) from the murine tumors initiated by oncogenic Braf (LSL-Braf(V600E)/TPO-Cre) and transfect the cells with pCMV6-SNAIL." (PMID 25076938, 2014). "The use of a mouse model in which the malignant transformation can only occur in differentiated thyroid cells expressing thyroid peroxidase (TPO) is a simple approach to answering the question of where stemness is derived from in thyroid cancer." (PMID 25076938, 2014). "Numerous genes have been used in thyroid cancer and include Tg, thyroid peroxidase (TPO), thyrotropin or thyroid stimulating hormone (TSH) receptor, and the sodium/iodide symporter (NIS)." (PMID 21969828, 2011). "Before testing the potential use of anti-TPO aAbs for immunotherapy of thyroid cancer by cytotoxic assays (ADCC and CDC), we first characterised the target and effector cells." (PMID 20145622, 2010). "We focused this study, until now the only one, on the possible use of anti-TPO aAbs in thyroid cancer immunotherapy to improve the efficiency of conventional treatments and especially in carcinoma that do not respond to radioiodine therapy." (PMID 20145622, 2010). "There is disagreement concerning the expression of thyroid peroxidase (TPO) in thyroid cancer, some studies finding qualitative as well as quantitative differences compared to normal tissue." (PMID 11556840, 2001). "The present results show that in about two-thirds of differentiated thyroid carcinomas, TPO protein is expressed, albeit to a more variable extent than normal; when present, TPO in malignant tissues is immunologically normal." (PMID 11556840, 2001). "Two studies used immune-affinity capture of EVs expressing specific surface proteins (2/40) and one study utilized a thyroid tissue-specific marker to isolate a subpopulation of EVs expressing thyroid peroxidase (TPO), which is a tissue-specific thyroid gland and thyroid cancer enriched protein." (PMID 41193833, 2025). "Other studies have also reported that thyroid cancer could be induced by 3 Gy of X-irradiation combined with the administration of a thyroid peroxidase inhibitor." (PMID 40076501, 2025). "However, there are still some patients with PTC whose thyroid cancer tissues show positive expression of TPO." (PMID 37407700, 2023). "Thyroid cancer cells are known to have variable and generally lower expression of TPO, which may have prognostic implications." (PMID 37352166, 2023). "Therefore, TPO expression is often used clinically to assist in the diagnosis of benign and malignant thyroid tumors with high sensitivity and specificity." (PMID 37407700, 2023). "However, Serum circulating antibodies, i.e., anti-thyroglobulin antibodies, anti-thyroid peroxidase and thyroid hormones in euthyroid thyroid cancer patients and healthy volunteers, are shown in." (PMID 35399732, 2022). "Restoring TPO expression may support the longer retention of radioiodine inside thyroid cancer cells." (PMID 36012698, 2022). "Similarly, while we demonstrated the TG and TPO re-expression in dedifferentiated thyroid cancer cells by Nkx2-1 transduction, we coincidentally observed cell death." (PMID 34748583, 2021).
thyroid cancer (continued). "The autoimmune response within the context of an antitumor immune response would be confirmed by the presence of anti-TG (AAT) and anti-TPO (ATPO) antibodies in about 20% of patients with thyroid carcinoma, with values twice higher in patients with PTC, compared to the general population." (PMID 31142293, 2019). "In thyroid cancer, TPO protein expression was lower than in paired malignant normal tissues." (PMID 28575127, 2017). "In our study, TPO levels represent a useful prognostic factor for differentiated thyroid cancer." (PMID 26300979, 2015). "The goal of this study is to analyze TPO immune expression in differentiated thyroid cancer, and to determine whether TPO has any prognostic value." (PMID 26300979, 2015). "Finally, recombinant human anti-TPO aAbs cannot yet be considered as an optimal tool for the development of a novel therapeutic approach for thyroid cancer." (PMID 20145622, 2010). "In this study, we hypothesised that human recombinant anti-TPO aAbs could be used to destroy thyroid tumour cells and thus to develop a complementary therapeutic approach in thyroid cancers." (PMID 20145622, 2010). "To evaluate if these anti-TPO aAbs may be useful tools in the treatment of thyroid carcinomas, we selected a human recombinant anti-TPO aAb and expressed it in baculovirus (B4) and in CHO cells (B4′)." (PMID 20145622, 2010). "On the basis of these observations, one could envision the use of anti-TPO aAbs as potential antigen-specific agents with cytotoxic activities for the treatment of thyroid carcinomas." (PMID 20145622, 2010). "The expression of Pax-8 and TTF-1 is low in thyroid carcinoma; and stable transfection with a Pax-8 expression vector in anaplastic thyroid carcinoma cell line, ARO, caused re-expression of endogenous NIS, TG, and TPO." (PMID 18682709, 2008). "However, a retrospective study concluded that the efficacy of CTCs in diagnosing thyroid cancer is still limited considering the number of CTCs and the antibodies against thyroid peroxidase (ATPO) values in a cohort of thyroid tumor patients divided into malignant and benign groups." (PMID 40095491, 2025). "In addition, we established BRAFV600E-driven transgenic mouse model of thyroid cancer (TPO-Cre/LSL-BrafCA) and demonstrated that Ng2 was significantly increased in tumor tissues from BRAF-mutant mice (BRAFV600E) compared with wild-type ones (BRAFWT) by qRT-PCR and immunofluorescence (IF) assays." (PMID 38795180, 2024). "Iodine concentration in thyroid cancer cells depends on iodine uptake, when the expression of the sodium iodine symporter is preserved on the cell membrane, and on iodine retention, due to preserved expression of thyroid peroxidase (TPO) involved in organification." (PMID 39272954, 2024). "In addition, this may be in relation to what has been reported in humans harboring variants in genes implicated in TH synthesis (NIS, TG, TPO, and SLC26A4); thyroid goiter with dyshormonogenesis may develop thyroid cancer later in life." (PMID 37964961, 2023). "Similarly, the combination of first thyroid cancer and second thyroid cancer may be triggered by the increased levels of thyroid globulin and thyroid peroxidase in patients." (PMID 34556087, 2021). "Finally, in an agreement with the previously established role of thyroid peroxidase (TPO) in oncogenic transformation in general, and its association with human thyroid carcinomas, our analysis has shown a strong downregulation of this transcript in all FTC samples." (PMID 27329729, 2016). "Therefore, TPO expressed at the surface of thyroid cancer cells can be recognised by anti-TPO autoantibodies (aAbs) and might constitute a potential target for antibody-specific immunotherapy." (PMID 20145622, 2010). "Therefore, due to the lack of iodide, TPO mutations may increase the risk of multinodular goiter and even thyroid cancer." (PMID 40665986, 2025).
thyroid cancer (continued). "To uncover the most distinct genes in different thyroid cancer subtypes, we screened BCL2, BHLHE40, MICAL2, TGM2, and TPO by comparing each pair of existing subtypes." (PMID 39872516, 2024). "FOXE1 regulates the transcription of thyroglobulin (TG), thyroperoxidase (TPO), NKX2.1, PAX8, Sodium/Iodine Symporter (NIS), and DUOX2, genes required for hormone synthesis, and also regulates PDGFA and ZEB1 in thyroid cancer." (PMID 39588344, 2024). "To further prove anti-tumor activity of mannose in primary thyroid cancers, we established a mouse model of BRAFV600E-derived papillary thyroid cancer (PTC) by crossing the BrafCA mice with TPO-Cre mice." (PMID 34886901, 2021). "Before the use of Nthy-ori 3-1 normal thyrocytes and FTC-133 thyroid cancer line as target cells in the ADCC and CDC models, TPO expression was determined on mRNA and protein levels in both cell lines." (PMID 31979029, 2020). "Non-I-131-avid metastases often demonstrate dedifferentiated thyroid cancer cells, which is accompanied by reduced expression of the sodium iodide symporter, the TSH receptor, and thyroid peroxidase." (PMID 29190950, 2017). "However, studies concerning TPO expression in thyroid cancer yielded discrepant data; some studies reported an inverse correlation between TPO and proliferative cell membrane antigen, whereas others pointed to a normal TPO expression in the majority of thyroid carcinomas (more than 65%)." (PMID 20145622, 2010). "Our in vitro data show that anti-TPO aAbs do exhibit some capacities to destroy NPA thyroid tumour cells by ADCC or CDC but in the present state, cannot be considered as suitable for thyroid cancer immunotherapy." (PMID 20145622, 2010). "Retinoids have been reported to induce the expression of TPO, TG, and NIS mRNAs in thyroid carcinoma cell lines." (PMID 18682709, 2008). "Earlier studies using either the TG or TPO promoter found that they were activated by TTF-1 and HNF3β/FoxA2 in thyroid carcinoma cell lines." (PMID 18682709, 2008). "The detection of thyroid-specific proteins, such as thyroglobulin (Tg), thyroid peroxidase (TPO) and thyroid stimulating hormone receptor (TSHR), may reflect the differentiation ability of thyroid cancer cells." (PMID 39349421, 2024). "According to other studies, TPO is highly expressed, mainly in normal thyroid tissue or benign lesions, whereas in thyroid cancer, its expression is reduced or absent." (PMID 39682560, 2024). "Some patients with thyroid cancer did not shed TPO cfRNA into the circulation and had measurable circulating TG, GFRA2, IYD cfRNA levels instead." (PMID 34512731, 2021). "Utility of thyroid-specific mRNA transcripts such as thyroid peroxidase (TPO), sodium-iodide symporter (NIS), thyroglobulin (TG), and thyroid stimulating hormone receptor (TSHR) in predicting thyroid cancer recurrences and metastases had been assessed previously using whole blood." (PMID 34512731, 2021). "To determine whether the TGFβ/SMAD pathway is activated in BRAFV600E-driven PTC in vivo, we performed pSMAD Western blots in tumor lysates from TPO-Cre/LSL-BrafV600E mice, which develop thyroid cancers with high penetrance by 5 weeks of age." (PMID 33890869, 2021). "We found that other circulating thyroid-specific targets such as TPO, IYD, TG, and GFRA2 cfRNA fell accordingly post-treatment for thyroid cancer, and could be potential biomarkers to reflect thyroid mass." (PMID 34512731, 2021). "Well-differentiated thyroid cancer exhibits active radioactive iodide uptake owing to the appropriate expression of iodide-handling genes, including sodium-iodide symporter (NIS), thyroid peroxidase (TPO), and thyroid-stimulating hormone receptor (TSHR)." (PMID 33499100, 2021). "Similar results were obtained in studies comparing TPO expression in thyroid cancer samples with that in paired normal thyroid tissue specimens." (PMID 28575127, 2017).
thyroid cancer (continued). "The presence of TPO in various thyroid carcinoma and metastases, but not in the other tissues, makes it tempting to target thyroid cancer cells with specific anti-TPO Abs." (PMID 20145622, 2010). "TPO is a crucial protein in thyroxine production that is nearly absent in thyroid cancers." (PMID 37795451, 2023). "However, these cells show reduced expression of the sodium/iodide symporter (NIS) and thyroid peroxidase (TPO) compared to thyroid epithelial cells, which may account for the lower values of radioiodine uptake and effective period in thyroid cancer tissue." (PMID 28389624, 2017). "Finally, the use of a mix of anti-TPO aAbs resulting in the simultaneous presence of multiple non-competing TPO epitopes should also improve detection of TPO on cancer cell surface, an essential feature for thyroid cancer treatment." (PMID 20145622, 2010). "Indeed, unlike other thyroid-specific antigens, such as thyroglobulin and TSH receptor that are no longer expressed in thyroid carcinomas, TPO expression persists even on poorly differentiated thyroid tumours." (PMID 20145622, 2010). "In terms of the comparison between SSc patients with and without thyroid cancer, various factors were analyzed, including age, the distribution of sexes, the type of SSc, and the presence of antibodies such as anti-nuclear antibodies (ANAs), ACAs, ATAs, anti-Tg, and anti-TPO." (PMID 38256549, 2024). "Thyroid carcinoma cells often do not express thyroid-specific genes including sodium iodide symporter (NIS), thyroperoxidase (TPO), thyroglobulin (TG), and thyrotropin-stimulating hormone receptor (TSHR)." (PMID 18682709, 2008).
goiter (60 papers, 2010 to 2025). Enlargement of the thyroid gland usually caused by lack of iodine in the diet, hyperthyroidism, or thyroid nodules. "In conclusion, mild TPO deficiency is an autosomal recessive disorder primarily characterized by goiter, increased FT3/FT4 ratios, elevated Tg levels, and normal anti-TPO and anti-Tg levels." (PMID 40665986, 2025). "Specifically, in addition to TPO gene mutations, goiter is a common manifestation TG gene mutations." (PMID 41394090, 2025). "For subclinical hypothyroidism, treatment is individualized, depending on factors such as TSH, anti-TPO levels, symptoms, pregnancy, goiter, and cardiovascular risk." (PMID 41552158, 2025). "TPO mutations are among the main causes of thyroid dyshormonogenesis, resulting in congenital hypothyroidism and goiter." (PMID 38542286, 2024). "In contrast to Patient #4, who presented with oligogenic variants of DUOX2, THRB, and TPO and underwent continuous follow-up owing to a simple goiter, Patient #15 had an enlarged nodular goiter and was finally diagnosed with thyroid follicular adenoma." (PMID 39029043, 2024). "Of the 17 cases with TPO variants, 9 presented normal thyroid shape and size, 6 were diagnosed with goiter, 1 showed thyroid dysplasia, and 1 was suspected with athyreosis." (PMID 35002963, 2021). "Previous studies showed that patients with CH and TPO mutations often presented with permanent CH and goiter." (PMID 35002963, 2021). "We assume that goiter development in patients with TPO mutations is a result of a combination of genetic and environmental factors." (PMID 34501348, 2021). "Macedonian cases harboring TPO mutations all had severe, goitrous CH, as is typical in this context, and the fetal goiter observed in one case is a rare, but recognized presentation." (PMID 32765423, 2020). "Many goiter patients with defects in the thyroid hormone biosynthesis have a mutation in the TPO gene." (PMID 24482635, 2014). "In this present study, we identified a homozygous c.2268dup mutation in the TPO gene in two sisters from Malaysian-Chinese family, with CH, with development of goiters later in their lives." (PMID 24745015, 2014). "Mutations in the TPO gene are the most common cause of dyshormonogenesis, which, in turn, is the second most common etiology of congenital hypothyroidism, often associated with goiter." (PMID 40650076, 2025). "The current study aimed to detect some TPO mutations associated with goiter in Iraqi patients." (PMID 24482635, 2014). "The literature suggests that TPO mutations may be associated with type 2A hypothyroidism, an autosomal recessive condition characterized by significantly low thyroid hormone levels and goiter after birth (PMID:28648508)." (PMID 40665986, 2025). "According to studies carried out in Toy Fox Terriers and Belgian cats, goiter in these animals was related to mutations in TPO, so the homology between these studies and the present case allows us to deduce that the enlargement of the thyroid may be due to defects in the organization of iodine." (PMID 40013294, 2024). "However, CH associated with goiter is often caused by defective Thyroid peroxidase (TPO) gene." (PMID 23737781, 2013). "These 10 cases of mild TPO deficiency leading to PIOD revealed several clinical characteristics, including early childhood onset, goiter, elevated FT3/FT4 ratios, elevated Tg levels, and normal anti-TPO and anti-Tg levels." (PMID 40665986, 2025). "Our case presented with goiter and tested positive for anti-TPO and TG, with ultrasound findings reporting a heterogeneous texture of the thyroid gland, multiple echogenic septae, and increased vascularity." (PMID 41024896, 2025). "Owing to residual TPO activity, the proband presented in childhood with goiter and abnormal thyroid function." (PMID 40665986, 2025).